RNU6-586P (RNA, U6 small nuclear 586, pseudogene)
Gene: Small nuclear RNA gene on chromosome 1 (67,196,140 to 67,196,243, forward strand). Ensembl gene ENSG00000253074.
Homologues: Orthologues: chimpanzee U6 (100% identical), dog RNU6-586P (73% identical). Paralogues in human: RNU6-330P (78% identical), RNU6-1251P (75% identical), RNU6-420P (75% identical), RNU6-529P (75% identical), RNU6-1029P (74% identical), RNU6-1099P (74% identical), RNU6-1329P (74% identical), RNU6-263P (74% identical), RNU6-296P (74% identical), RNU6-49P (74% identical), RNU6-74P (74% identical), RNU6-787P (74% identical), and 1282 more.